AGT (angiotensinogen)
Diseases named in the same sentence as AGT in open-access papers (continued):
Sharing a sentence is not in itself a finding about the gene and the disease.
Hypertension (continued). "In addition to GRK4, gene polymorphisms related to the renin-angiotensin-aldosterone system (RAAS), such as angiotensin converting enzyme (ACE), angiotensinogen (AGT), angiotensin II type 1 receptor (AGTR1), and aldosterone synthase (CYP11B2), have been reported to be associated with hypertension." (PMID 22518293, 2012). "We genotyped five polymorphisms of the AGT, ACE, AT1R, 5-HT2A, and 5-HTT genes in 245 patients with Hypertrophic Cardiomyopathy (HCM; 205 without an identified sarcomeric gene mutation), in 145 patients with LVH secondary to hypertension, and 300 healthy controls." (PMID 20594303, 2010). "However, the results for A6G of AGT gene revealed significant differences in allele and genotype frequencies in essential hypertension with or without T2DM (p < 0.001)." (PMID 19243623, 2009). "Human renin from the fetus crosses the placenta to cleave human angiotensinogen that cannot be cleaved by rat renin, resulting in increased angiotensin II, AT1-AA production and hypertension." (PMID 40777009, 2025). "IONIS-AGT-LRx, an antisense oligonucleotide (ASO) targeting angiotensinogen (AGT) mRNA, represents a novel therapeutic strategy for hypertension management by inhibiting the RAAS upstream at the hepatic level." (PMID 40454237, 2025). "For instance, zilebesiran, an siRNA therapeutic targeting angiotensinogen, has been evaluated in the KARDIA-1 trial, demonstrating significant blood pressure reductions in patients with mild to moderate hypertension." (PMID 40182424, 2025). "In the succeeding paragraphs, we highlight the pertinent findings of renin, AGT and ACE SNPs in relation to PE, PIH and hypertension." (PMID 38411777, 2024). "Proteins including AGT, ALB, APOL1, and UMOD had the highest disease scores (76–100% confidence) for CKD and hypertension." (PMID 38402394, 2024). "Two RNA-based therapeutics capable of silencing hepatic AGT, IONIS-AGT-LRx and ALN-AGT, are currently being tested to treat hypertension." (PMID 39852196, 2024). "Then the renin acts on the angiotensinogen to produce angiotensin I (Ang I), which is transformed by the ACE into angiotensin II (Ang II), the major player in hypertension." (PMID 38345042, 2024). "Elevated levels of Ang II and its receptor type 1 angiotensinogen (AT1) promote cardiac remodeling and play an important role in the occurrence and development of hypertension." (PMID 36992835, 2023). "The system involves the conversion of angiotensinogen into angiotensin I and then converted into angiotensin II by angiotensin I‐converting enzyme (ACE), resulting in hypertension." (PMID 37181307, 2023). "The antisense AGT inhibitor IONIS-AGT-LRX significantly reduces plasma AGT levels and is well-tolerated in phase II trials as a monotherapy and as an add on to existing hypertension drugs." (PMID 37372091, 2023). "Previous studies suggest that increased renin and angiotensinogen (AGT) levels lead to an increased ANGII concentration, thereby stimulating hypertension and organ damage." (PMID 35203286, 2022). "In summary, AGT suppression lowers BP to the same degree as classical RAS blockers like ACE inhibitors and ARBs in a variety of hypertension models, and this effect is largely due to interference with tissue angiotensin generation." (PMID 35904033, 2022). "This ASO, developed by Ionis Pharmaceuticals, Inc., is designed to target angiotensinogen (AGT) and, consequently, inhibit RAAS pathways, acting as a therapeutic approach for the treatment of hypertension and HF conditions." (PMID 35681500, 2022). "Collectively these data indicate that the development of hypertension in response to elevated AngII and HS intake is the result of reduced TNFR1 activity that leads to an enhancement in hypertension and intrarenal AGT formation." (PMID 34427402, 2021). "Recent studies on experimental animal models and transgenic mice have documented the involvement of the adipose AGT in the activation of the RAAS and the development of hypertension." (PMID 33925539, 2021).
Hypertension (continued). "Our previous work showed DMF administration in pregnancy protects adult offspring against hypertension programmed by antenatal DEX plus postnatal high-fat diet, which was relevant to downregulated mRNA expression of renin, AGT, ACE, and AT1R." (PMID 33669059, 2021). "The Met174 allele of AGT p.Thr174Met might increase the plasma levels of AGT and Ang II, thereby increasing vasoconstriction, VSMC proliferation, and lipid deposition; this allele participates in the pathogenesis of atherosclerosis, hypertension, and MI and increases the MI risk." (PMID 34025779, 2021). "Combining the outcomes from both target lists, we selected ACE, AGT, AGTR1, and REN as important targets in COVID-19 for hypertension patients." (PMID 34067609, 2021). "Since uAGT provides a specific index of intrarenal AGT production in AngII‐dependent hypertension, the results suggest that the TNFR1KO mice had higher levels of intrarenal AngII." (PMID 34427402, 2021). "Here, we revealed that CG200745 reversed HFD-induced increase in HDAC activity, kidney angiotensinogen expression, and consequent increase in serum Ang II resulting in vascular contraction and amelioration of HFD-induced hypertension for the first time." (PMID 31655853, 2020). "Our previous and the present study also revealed increased angiotensinogen in the kidney and consequent increase in Ang II in the plasma in HFD-induced hypertension proving importance of renal angiotensinogen expression." (PMID 31655853, 2020). "The PVN is a vital cardiovascular center which expresses major RAS components, such as AGT, ACE-1, AT1, and contributes to hypertension in CKD." (PMID 31392659, 2020). "Using 4,150 Thais recorded in the Electricity Generating Authority of Thailand (EGAT) study, we examined the association of rs1799752, rs699, rs5186, and rs1799998 located in or near ACE, AGT, AGTR1, and CYP11B2 genes in hypertension." (PMID 31511791, 2019). "When female transgenic mice carrying the human AGT gene were mated with male mice carrying the human REN gene, they developed preeclampsia (hypertension and proteinuria) in mid-gestation." (PMID 31551925, 2019). "Several genes including WNK1, WNK4, Bp1, Bp2, AGT, and ACE were reported to be involved in hypertension." (PMID 30875817, 2019). "Renin in turn transforms angiotensinogen into angiotensin I, which is then converted into angiotensin II by ACE, resulting in hypertension." (PMID 31379972, 2019). "Angiotensinogen (AGT), the initial substrate of the renin-angiotensin-aldosterone system pathway, is involved in the development of hypertension in humans and other animals." (PMID 30700972, 2019). "A growing body of evidence has shown that urinary angiotensinogen is a specific biomarker for the status of the intrarenal RAAS, hypertension and renal disease." (PMID 29600408, 2018). "Sodium retention, plasma rennin activity, angiotensinogen, angiotensin II and aldosterone values display significant increase during obesity and additionally insulin resistance and inflammation may promote an altered profile of vascular function and consequently leads to hypertension." (PMID 30526686, 2018). "Thus, investigations of urinary angiotensinogen have been widely spread in the world and a growing body of clinical evidence has indicated that augmented urinary angiotensinogen levels are correlated with clinical parameters in patients with hypertension and CKD." (PMID 29600408, 2018). "In any case, urinary angiotensinogen is a useful biomarker for identifying the status of the intrarenal RAAS, hypertension and renal disease." (PMID 29600408, 2018). "The Ren-2 rat is characterized by severe hypertension, LVH, suppression of the kidney renin-angiotensin system and unchanged or suppressed levels of plasma renin, Ang I and II and angiotensinogen compared to wildtype rats." (PMID 29702551, 2018).
Hypertension (continued). "AGT and ACE are part of Renin-Angiotensin System pathway (KEGG, map04614), involved in BP homeostasis, fluid-electrolyte balance, and essential hypertension." (PMID 29912962, 2018). "Renin (EC 3.4.23.15) converts angiotensinogen to angiotensin I, and it will be converted to biologically active angiotensin II by angiotensin-I converting enzyme (ACE, peptidyldipeptide hydrolase, EC 3.4.15.1), which ultimately leads to hypertension." (PMID 28282929, 2017). "Several studies have established the evidence of a genetic linkage between the angiotensinogen gene (AGT) and essential hypertension." (PMID 28828324, 2017). "Hypertension may also be mediated through increased vascular and sympathetic tone created by reduced bioavailability of nitric oxide (NO) because of oxidative stress, and increased expression of angiotensinogen by adipose tissue leading to an activation of the renin-angiotensin system." (PMID 25774201, 2015). "Notably, the expression level of AGT was much stronger in case I (PKD-CKD, eGFR 69 mL/min/1.73 m2 with hypertension) than that in case II (PKD-ESRD, eGFR 11 mL/min/1.73 m2 with hypertension, pre-dialysis) suggesting that urinary AGT/Cr may be more useful in the early stage of renal disease." (PMID 26092580, 2015). "Genes associated with renin-angiotensin-aldosterone system, such as angiotensinogen (AGT), angiotensin converting enzyme (ACE) and angiotensin II receptor 1 (AGTR1), were the most extensively studied as hypertension candidate genes." (PMID 25313554, 2014). "In the current study, we evaluated whether seven SNPs in the AGT gene affect risk of CHD and HF in high-risk hypertensive individuals randomized to one of three classes of antihypertensive treatment as part of the Genetics of Hypertension Associated Treatment Study (GenHAT) using a case-only design." (PMID 25278896, 2014). "At last, we determined its ability to delivery a theraputic AGT shRNA to BRL-3A cells, one of the optimal therapeutic targets for hypertension therapy, and observed the gene silencing effect." (PMID 23894329, 2013). "Therefore, suppressing of AGT expression may be a new strategy for the treatment of hypertension." (PMID 23894329, 2013). "In addition, studies in transgenic mice demonstrate that adipose-derived angiotensinogen may also contribute to the systemic RAAS pool, and the relationship between obesity and hypertension may be directly explained by angiotensinogen secretion by the rodent adipocyte." (PMID 22475205, 2012). "Transcription of angiotensinogen seems also to be regulated by PPARα, although the value of PPARα as a therapeutic target in RAAS dependent hypertension should be evaluated." (PMID 20613959, 2010). "Therefore, A6G polymorphism of the AGT gene could be a potential genetic marker for increased susceptibility to essential hypertension with or without T2DMin Malaysian subjects." (PMID 19243623, 2009). "Furthermore, considering the hypertension-associated SNPs, whilst the Kashmiri group had a significantly lower MAF for the CYP3A5 g.6980G>A SNP compared to the other groups, this language group also had the highest MAF for the AGT g.802C>T SNP and the second highest MAF for the GNB3g.4423C>T SNP." (PMID 18248681, 2008). "The AGT M235T polymorphism has been shown to be positively related to essential hypertension and MI but other studies found no relation at all between the marker and disease and few reports exist to confirm an association with plasmatic AGT concentration level." (PMID 18637188, 2008). "Furthermore, AngII/AT1R also increases the tubular expression of angiotensinogen, ACE, renin, and AT1R, which aggravates hypertension and kidney injury." (PMID 40422232, 2025). "The angiotensinogen (AGT) gene and ESR genes may all be involved in the etiology of HC-induced hypertension." (PMID 41323407, 2025).
Hypertension (continued). "Once secreted, angiotensinogen undergoes enzymatic cleavage by renin, which is primarily produced by the kidneys in response to RAS activation, into angiotensin I (Ang I), with any disruption in this balance contributing to hypertension." (PMID 40969606, 2025). "Additionally, while considered a low-renin model of hypertension, the SHR model demonstrates increased angiotensinogen production, subsequently increasing circulating angiotensin II." (PMID 39452073, 2024). "Among the 44 articles selected for full reading, nine were not focused on RNAi targeting AGT for hypertension treatment, 29 were not fully available, and 12 were unavailable for retrieval." (PMID 39852196, 2024). "Additionally, proteins such as AGT, ALB, APOL1 and UMOD had the highest disease scores (76–100% confidence) for hypertension and CKD." (PMID 38402394, 2024). "Reduction in the expression of renin, AGT, ACE1, and AT1R following STS-loaded NP therapy may help mitigate the detrimental effects of CKD-induced hypertension." (PMID 39765901, 2024). "In a normal healthy pregnancy, the levels of renin, angiotensinogen, angiotensin I and II, and aldosterone are elevated compared to non-pregnant women, but a vasodilatory state is present such that hypertension does not typically occur." (PMID 37089425, 2023). "Monocyte/macrophage express ATR, angiotensinogen, renin, as well as angiotensin peptide hormone thus, monocyte/macrophage activity and function is modulated by RAS components during hypertension." (PMID 37854465, 2023). "In contrast, MTHFR C677T, AGT T174M, and AGTR1 A1166C did not represent a higher risk for hypertensive disease." (PMID 36845669, 2023). "Since hypertension will normally suppress renin release, it is not unlikely that low systemic RAS activity indeed occurs in combination with high renal RAS activity (due to enhanced AGT uptake)." (PMID 35710133, 2022). "In diabetic nephropathy or Ang II-induced hypertension, for example, components of the RAS like angiotensinogen, ACE, (pro)renin, and AT1 receptors are upregulated along the nephron and in the medullary region leading to high levels of intratubular Ang II." (PMID 35511367, 2022). "Upregulation of intrarenal angiotensinogen and ACE expression and down-regulation of ACE2 and MasR gene expression contributed to obtaining a high AngII/Ang 1-7 ratio, which facilitated the development of hypertension." (PMID 36148474, 2022). "A more likely scenario is that high blood pressure (e.g., after infusing Ang II) affects glomerular filtration, thus resulting in the accumulation of filtered hepatic AGT into the kidney and allowing increased Ang II generation." (PMID 35710133, 2022). "ASrAogen transgenic rats, with decreased glial expression of angiotensinogen, do not develop hypertension and obesity during aging, but its plasma levels of leptin are lower than in normal rats." (PMID 33572630, 2021). "Research has revealed that, in transgenic rats exhibiting the overexpression of the angiotensinogen gene, the contributing role of AngII in the development of myocardial hypertrophy appears to be independent of hypertension." (PMID 33986629, 2021). "In addition, obesity-related hypertension is due to activation of adipose tissue-tumor-necrosis-factor-alpha (TNF-α) and expression of angiotensinogen gene by nuclear factor kappa B (NF-κB) signaling pathway." (PMID 34806090, 2021). "For example, HRP can alleviate organ damage and eyeball diseases caused by diabetes and hypertension, but it does not reduce the hypertension of renin and angiotensinogen (AGT) overexpressing rats." (PMID 34057312, 2021). "Another study investigated the effects of dual RAS blockade with ACEI and ARB on ACE2 expression, hypertension and renal proximal tubular cell (RPTC) apoptosis in type 1 diabetic Akita angiotensinogen (Agt)-transgenic (Tg) mice that specifically overexpress Agt in RPTCs." (PMID 33762942, 2021).
Hypertension (continued). "Mice lacking Angiotensinogen or Ang II receptor genes show decreased obesity, insulin resistance, and hypertension, supporting the notion that RAAS activation contributes to COVID-19 comorbidities." (PMID 33757938, 2021). "RCC risk has been found to be associated with interactions between alcohol consumption and ADH726; sodium and hypertension and AGTR, AGT and ACE31; calcium and vitamin D intake and RXRA28; tobacco smoking and NAT2, CYP1A1 and GSTM125; and meat-cooking mutagens and ITPR2 and EPAS127." (PMID 31924838, 2020). "Thus, patients with M/M and M/T genotypes of the AGT gene and with comorbid COPD and hypertension had the highest test parameters of oxidative stress compared with Group 1 and controls." (PMID 32025262, 2019). "It should be emphasized that among patients with M/M and M/T genotypes of the AGT gene, significantly higher investigational values of H2O2 and О2•- were observed in patients with comorbid COPD and hypertension compared with the group of COPD-only patients, a mean 1.6-fold difference." (PMID 32025262, 2019). "Moreover, it remains to be established what effects are caused by the replacement of threonine with methionine of the AGT gene in virtually healthy individuals and patients with COPD+hypertension." (PMID 32025262, 2019). "We did not observe any significant correlations between ACE and AGT gene polymorphisms and parameters of oxidative stress in a setting of comorbid COPD and hypertension." (PMID 32025262, 2019). "Our previous study has not shown the different alleles of the ACE and AGT genes to have any significant influence on the incidence and course of COPD, hypertension, or a combination of the two." (PMID 32025262, 2019). "Despite lack of effect on body composition under resting conditions, adipose deletion of angiotensinogen attenuates HFD-induced metabolic dysfunction (e.g., weight gain, glucose intolerance, dyslipidemia) in male mice, as well as hypertension in male and female mice." (PMID 31262355, 2019). "In the present study, IFN-γ expression in the kidney of the TSF group was significantly attenuated, indicating that TSF could reduce AGT production by reducing the expression of IFN-γ and thus ameliorate the development of hypertension." (PMID 29682583, 2018). "miR-483-3p expression downregulated angiotensinogen and angiotensin-converting enzyme (ACE) and could be a novel therapeutic agent for hypertension management." (PMID 29914215, 2018). "Aliskiren is a direct rennin inhibitor which blocks the RAAS at the first stage, decreases the activity of rennin, prevents the conversion of angiotensinogen to Ang and reduces the generation of Ang II and ALD to execute its role for the treatment of hypertension." (PMID 28690496, 2017). "The AGT and AGTR1 genes may be involved in common elements of the pathogenesis of hypertension, PE, and GH." (PMID 27910864, 2016). "Urinary angiotensinogen and intrarenal angiotensin II increased with angiotensin II mediated hypertension but not in rats with hypertension treated with deoxycorticosterone acetate/high salt diet." (PMID 26719973, 2015). "Increased AGT production by white adipose tissue in this mouse model not only induces hypertension; it also increases lipogenic gene expression, leading to abnormal fat distribution." (PMID 20613959, 2010). "In accordance with two of them including one German dataset, the present study fails to find an effect of the AGT or ACE genotype on the severity of hypertension." (PMID 15642127, 2005). "In the present study, the AGT TT genotype was negatively correlated to hypertension in women only while no sex-specific effect of the ACE gene was shown." (PMID 15642127, 2005). "Zilebesiran and IONIS-AGT-LR are novel RNA-based therapeutics that target angiotensinogen (AGT) synthesis in the liver, representing a possible shift in the management of hypertension in OSA, a phenotype characterized by RAAS hyperactivation, nocturnal hypertension, and aldosterone excess." (PMID 40364148, 2025).